EGFR (epidermal growth factor receptor)
Diseases named in the same sentence as EGFR in open-access papers (continued):
Sharing a sentence is not in itself a finding about the gene and the disease.
colorectal cancer (continued). "One suggested anti‐EGFR resistance mechanism in colorectal cancer (CRC) is aberrant MEK–AKT pathway activation through HER2 up‐regulation." (PMID 26690310, 2016). "This relationship has also been observed in BRAFV600E colorectal cancer and the increase in pEGFR as well as total EGFR levels in Db-treated 2341 cells, suggests a similar feedback mechanism in these mouse glioma cells." (PMID 27713119, 2016). "It has been reported recently that KRAS and BRAF mutations were negatively correlated with the response to targeting EGFR treatment in lung and colorectal cancers." (PMID 26909593, 2016). "To gain further insight into the mechanism of how AdC68-CTB and Hu5-CTB suppress the growth of colorectal cancer cells, we evaluated the ability of the recombinant adenovirus to inhibit the EGFR pathway activity." (PMID 27058423, 2016). "Metastatic colorectal cancer treatment frequently combines surgical resection with adjuvant therapies that include monoclonal antibodies, such as EGFR-targeted antibodies (cetuximab and panitumumab)." (PMID 27043547, 2016). "It was reported recently that amplification of MET, FGFR1 and ERBB2 was involved in EGFR therapeutic resistance in colorectal cancer." (PMID 27738318, 2016). "In particular he spoke about colorectal cancer and the multistep evolution of resistance to epidermal growth factor receptor (EGFR) blockade." (PMID 26823684, 2016). "The therapeutic arsenal available to treat colorectal cancer has recently been reinforced with two anti-EGFR monoclonal antibodies (mAbs i.e., cetuximab and panitumumab)." (PMID 27102434, 2016). "Blockade of the epidermal growth factor receptor (EGFR) with the monoclonal antibodies cetuximab or panitumumab is effective in a subset of colorectal cancers (CRCs), but the emergence of resistance limits the efficacy of these therapeutic agents." (PMID 27929064, 2016). "Recently, we also reported that high miR-31 expression was associated with shorter progression-free survival in patients with colorectal cancer treated using anti-epidermal growth factor receptor (EGFR) therapy." (PMID 26871294, 2016). "It is now widely accepted that therapeutic antibodies targeting epidermal growth factor receptor (EGFR) can have efficacy in KRAS wild-type advanced colorectal cancer (CRC) patients." (PMID 27509063, 2016). "Cetuximab, a monoclonal antibody against the epidermal growth factor receptor (EGFR), has been successfully used to treat some patients with colorectal cancer and those with head and neck squamous cell carcinoma (HNSCC)." (PMID 27399917, 2016). "Here, we evaluated the efficacy of adenovirus-mediated anti-EGFR (Ad-anti-EGFR) antibodies against colorectal cancer in mice." (PMID 27058423, 2016). "Both molecular pathways are connected by EGFR that has improved colorectal cancer classification and treatment." (PMID 26801617, 2016). "The anti-EGFR monoclonal antibodies cetuximab and panitumumab are administered to treat colorectal cancer patients with wild-type RAS tumors, and demonstrated to improve the survival of patients." (PMID 27659529, 2016). "In conclusion, we have demonstrated the antitumor effects of rMV-SLAMblind against nectin-4-positive colorectal cancer cells, including cells resistant to EGFR inhibitors, indicating that it is a potential novel therapy for colorectal cancers." (PMID 27090874, 2016). "Mutation analysis of the Kras oncogene has now been established as a predictive biomarker in colorectal cancer, which signifies that wild-type Kras should respond to anti- EGFR treatment." (PMID 27888800, 2016). "Some colorectal cancer patients respond well to treatment with anti-EGFR antibodies, however response is almost invariably followed by acquired resistance." (PMID 27929064, 2016). "It has been demonstrated that only patients with WT KRAS tumors benefit from anti-EGFR monoclonal antibodies treatment in colorectal cancer, while KRAS mutations confer resistance to anti-EGFR therapy." (PMID 27416070, 2016).
colorectal cancer (continued). "Further, studies reported that exosomes from colorectal cancer contain full length, signalling-competent epidermal growth factor receptor (EGFR) ligands." (PMID 27756426, 2016). "The aim of this study was to assess the mutations of the most commonly affected 5 genes in the targetable EGFR-pathway in UrC and comapre their frequencies to those of found in urothelial and colorectal cancer." (PMID 27283768, 2016). "The roles played by EGFR proved to be central in colorectal cancer patients, who often present an addiction to this pathway." (PMID 27708224, 2016). "In colorectal cancers the limitations imposed by the emergence of drug resistance are manifest during treatment with the anti-EGFR antibodies cetuximab or panitumumab." (PMID 27929064, 2016). "The RNF43 and ZNRF3 mutant colorectal cancer cell lines were all MSI, and all harbour a mutation within the EGFR-MAPK signalling pathway." (PMID 27661107, 2016). "EGFR is expressed in epithelial cells of gastric cancer at a relatively high level, and the mutation rate of KRAS in gastric cancer is much lower than that in colorectal cancer (4.2%), and therefore EGFR-targeted therapy is the present research hot spot." (PMID 26880889, 2016). "EGFR and its ligands play central roles in the development of epithelial tumors, including colorectal cancers." (PMID 27344184, 2016). "Amphiregulin (AREG) and epiregulin (EREG), which are ligands of EGFR, are overexpressed in colorectal cancer at both the mRNA and protein levels." (PMID 27344184, 2016). "The epidermal growth factor receptor (EGFR) is a receptor tyrosine kinase that plays a key role in the development and progression of some tumours, particularly colorectal carcinoma." (PMID 27083443, 2016). "Cetuximab and Panitumumab are monoclonal antibodies directed against the epidermal growth factor receptor (EGFR) clinically used for the molecular targeted therapy on colorectal carcinoma." (PMID 27632281, 2016). "For example, in colorectal carcinomas, resistance to epidermal growth factor receptor (EGFR) inhibitors has recently been observed after a fairly constant time period, supporting the notion that resistance is a fait accompli." (PMID 26845763, 2016). "Recently, another study in colorectal cancer highlights the role of c-Met in mediating primary and secondary resistance to anti-EGFR therapies and encourages the use of c-Met inhibitors in patients displaying resistance as a result of c-Met amplification." (PMID 25588551, 2015). "In colorectal cancers, several miRNAs are known to be deregulated with target genes in the downstream effectors of epidermal growth factor receptor (EGFR)." (PMID 26090613, 2015). "Activating mutations in the Kirsten rat sarcoma viral oncogene homolog (KRAS) loci are largely predictive of resistance to epidermal growth factor receptor (EGFR) therapy in colorectal cancer (CRC)." (PMID 25823645, 2015). "Many epithelial tumors rely on the activation of EGFR and in colorectal cancer EGFR gene amplification predicts a better response to the anti EGFR antibody therapy with Cetuximab." (PMID 25987127, 2015). "A previous study has demonstrated that EGFR-dependent activation of the MEK/ERK signaling pathway stimulates Claudin-2 expression in colorectal cancer cells." (PMID 25823815, 2015). "Together, these results suggested that integrin-β1 and integrin-α2 upregulated MMP-7 expression through YAP, MRLC and EGFR by generating a positive feedback loop on stiffer substrates in colorectal cancer." (PMID 26344692, 2015). "In colorectal carcinoma, numerous clinical studies have shown that anti-EGFR therapies are effective only in a subset of patients with colorectal cancer." (PMID 25894462, 2015). "Recently, mutations in KRAS have been detected in circulating tumor DNA in colorectal cancer patients with KRAS-wildtype (wt) cancers who had progressed on anti-EGFR therapy." (PMID 26474549, 2015).
colorectal cancer (continued). "Systemic treatment for patients with RAS wild type (wt) colorectal cancer (mCRC) includes anti– epidermal growth factor receptor (EGFR) monoclonal antibody (mAb) treatment with either cetuximab or panitumumab as monotherapy or in combination with chemotherapy." (PMID 26309164, 2015). "This is exemplified by the differential activation of EGFR-driven feedback control in BRAF-mutant colorectal cancer and melanomas in response to BRAF inhibition." (PMID 25885672, 2015). "This will provide definitive insight into EGFR as a tissue-based biomarker in patients with colorectal cancer and other malignancies." (PMID 26149458, 2015). "Amphiregulin, a ligand of the epidermal growth factor receptor (EGFR), is associated with the efficacy of cetuximab, an antibody against EGFR, as treatment for colorectal cancer (CRC)." (PMID 26569500, 2015). "Abundant studies also indicate that epidermal growth factor receptor (EGFR) activation is a causal driver of many cancers, including breast, lung, brain, and colorectal cancer." (PMID 26683696, 2015). "Retrospective data demonstrating a lack of response of patients with KRAS exon 2 mutant, and now extended RAS mutant, metastatic colorectal cancer to anti-EGFR therapy has changed the focus of colorectal cancer treatment to one of personalized cancer care." (PMID 26136684, 2015). "EGFR over-expression in colorectal cancer as determined by immunohistochemistry has led to initial clinical trials investigating patient selection for cetuximab and panitumumab therapies and shown promising results." (PMID 26149458, 2015). "The anti-epidermal growth factor receptor (EGFR) monoclonal antibodies (moAbs) cetuximab or panitumumab are administered to colorectal cancer (CRC) patients who harbor wild-type RAS proto-oncogenes." (PMID 26508446, 2015). "Monoclonal antibodies (mAbs) against the epidermal growth factor receptor (EGFR) are used in the treatment of advanced colorectal cancer (mCRC)." (PMID 26309164, 2015). "Irrespective of EGFR IHC status, a significant proportion of RAS wild type colorectal cancers are resistant to cetuximab, which suggests other EGFR-mediated or related mechanisms, contribute to this paradox." (PMID 26149458, 2015). "Here we use colorectal cancer (CRC) as a model to study how the acquisition of resistance to EGFR-targeted therapies can be restrained." (PMID 26392303, 2015). "In colorectal cancer cells, Caco-2 and HT-29, curcumin down-regulated the transcription factor, Egr1, and the expression of EGFR, thereby inhibiting colorectal cancer cell growth." (PMID 25665066, 2015). "Clinical studies thus far include targeting molecules that fall directly within the canonical MAPK pathway, such as MEK in melanoma and molecules that are membrane receptors activated due to feedback mechanisms, such as EGFR in colorectal cancer." (PMID 26284586, 2015). "EGFR protein expression in colorectal cancer has been widely reported as membranous; however, numerous studies have noted the expression of EGFR within the cytoplasm of tumoural cells." (PMID 26149458, 2015). "Bevacizumab (anti-VEGF antibody) and cetuximab (anti-EGFR antibody) are integral portion of the treatment guidelines for colorectal cancer and prediction of treatment response to these agents is currently based on the tumor’s molecular profile." (PMID 26207380, 2015). "In colorectal cancer, EGFR promoter hypermethylation made worse median progression-free survival and worse median overall survival." (PMID 25959250, 2015). "Gefitinib (Iressa, ZD-1839), a small molecule tyrosine kinase inhibitor (TKI) of the epidermal growth factor receptor (EGFR) pathway, is currently under investigation in clinical trials for the treatment of colorectal cancer (CRC)." (PMID 26542452, 2015). "Even with the extensive molecular characterisation of colorectal cancer, there are few molecular markers implemented in the clinical setting to determine clinical efficacy of anti-EGFR therapies." (PMID 26149458, 2015).
colorectal cancer (continued). "c.351A > C (substitution) in codon 117 just like c.436G > C (Substitution) has therapeutic implications in colorectal cancer and is known confer reduced sensitivity to anti-EGFR antibodies like cetuximab/panitumumab." (PMID 26315110, 2015). "Previous findings indicated that EGFR gene copy number (GCN) correlated with clinical outcome during anti-EGFR treatment in colorectal cancer patients." (PMID 25943333, 2015). "Here, the authors show that RHBDD1, a rhomboid intramembrane serine protease, promotes tumor growth in colorectal cancer via cleavage and secretion of TGFα, and activation of the EGFR/Raf/MEK/ERK signalling pathway." (PMID 26300397, 2015). "Detection of acquired resistance mutations through ctDNA analysis has been previously demonstrated in colorectal cancer with the evolution of mutant KRAS to EGFR blockade." (PMID 26524482, 2015). "Prognoses for patients with colorectal cancer (CRC) have improved significantly with the introduction of molecular-targeted drugs such as anti-epidermal growth factor receptor agents (anti-EGFR)." (PMID 25636897, 2015). "EGFR immunoprecipitated together with MET in cetuximab-resistant colorectal cancer cells, and this interaction was also observed in parental cells by TGFα stimulation." (PMID 26318427, 2015). "KRAS mutation testing has become mandatory prior to the administration of therapy with the anti-EGFR antibodies, cetuximab or panitumumab, for patients with advanced colorectal cancer." (PMID 25674493, 2015). "Originally, overexpression of EGFR was discovered as a biomarker for colorectal cancer and enlisted in clinical trials for an anti-EGFR mAb, Erbitux." (PMID 26858745, 2015). "The most relevant case is that of cetuximab, a chimeric IgG1 monoclonal antibody (mAb) against the epidermal growth factor receptor that is approved for use in colorectal cancer and squamous-cell carcinoma of the head and neck." (PMID 26263923, 2015). "Somatic DNA mutations of selected genes, which either had known importance in colorectal cancer or belonged to the EGFR signaling pathway, were identified." (PMID 25965827, 2015). "Somatic mutations in KRAS, NRAS, and BRAF genes are related to resistance to anti-EGFR antibodies in colorectal cancer." (PMID 25954997, 2015). "Recent small studies have suggested a benefit from a retreatment strategy in colorectal cancer with the use of anti-EGFR therapy." (PMID 26474549, 2015). "Mutations in the KRAS proto-oncogene are now widely recognized to be predictive for primary as well as acquired resistance to tailored therapy with anti-EGFR antibodies in colorectal cancer." (PMID 25568935, 2015). "Aberrant over-expression of this biomarker has been a widely investigated therapeutic target in a range of solid tumours including colorectal cancer (CRC) with different anti-EGFR therapies being considered." (PMID 26149458, 2015). "According to current clinical guidelines mutational analysis for KRAS and NRAS is recommended prior to EGFR-directed therapy of colorectal cancer (CRC) in the metastatic setting." (PMID 26220423, 2015). "In a similar fashion, treatment with trastuzumab or cetuximab prior to α4-1BB agonist therapy boosted ADCC and NK cell responses to HER2+ breast cancer or EGFR+ head and neck and colorectal carcinomas, respectively." (PMID 26106583, 2015). "Numerous clinical studies have shown that anti-EGFR therapies are effective only in a subset of patients with colorectal cancer." (PMID 25267307, 2014). "We have found no clear evidence to support an association between the KRAS-LCS6 genotype and overall or progression-free survival among colorectal cancer patients, even after conducting subgroup analyses by stage and anti-EGFR treatment status." (PMID 24890702, 2014). "Recently, cetuximab and panitumumab as EGFR monoclonal antigens have been made available for the treatment of colorectal cancer." (PMID 24517087, 2014).
colorectal cancer (continued). "It is now well established that KRAS mutations are the main reason for resistance to anti-epidermal growth factor receptor (EGFR) antibodies, and account for nearly two-thirds of EGFR downstream effector alterations in colorectal cancer." (PMID 25491325, 2014). "In most of these studies, KRAS genotyping was performed on primary colorectal cancers, whereas anti-EGFR antibodies were used to treat the metastatic disease." (PMID 24884535, 2014). "The prepared EGF-QDs exhibited optimal pharmacokinetics and superior docking ability to EGFR, which allowed quantifiable imaging of EGFR expression in human colorectal cancer xenografts in mice." (PMID 25988156, 2014). "A constitutive activation of protein kinase B (AKT) in a hyper-phosphorylated status at Ser473 is one of the hallmarks of anti-EGFR therapy-resistant colorectal cancer (CRC)." (PMID 25365190, 2014). "A first-line therapy for patients with advanced colorectal cancer is the anti-EGFR (epidermal growth factor receptor) drug cetuximab; however, this is was thought to be ineffective for patients with KRAS mutations." (PMID 25109951, 2014). "Having again the EGFR inhibitors as a paradigm, this is the case of K-Ras mutations leading to constitutive activation of the Ras/MAPK signaling pathway and mediating both intrinsic or acquired resistance to the anti-EGFR mAb cetuximab in colorectal cancers." (PMID 23992330, 2014). "The survival rate of colorectal cancer (CRC) patients carrying wild-type KRAS is significantly increased by combining anti-EGFR monoclonal antibody (mAb) with standard chemotherapy." (PMID 25260023, 2014). "EGFR and IGF-IR signaling play critical roles in many types of cancer and our group found that ARNO and other cytohesins enhance EGFR activation in the colorectal cancer cells." (PMID 24618737, 2014). "Here, we report, for the first time, the results of administering dual EGFR inhibition (erlotinib plus cetuximab) together with an anti-angiogenic agent (bevacizumab) in patients with heavily-pretreated colorectal cancer." (PMID 25594061, 2014). "In colorectal cancer, anti-EGFR antibodies are routinely used as second-line therapy of KRAS wild-type tumors." (PMID 24894453, 2014). "EGFR is over expressed in many types of cancers, especially colorectal cancer, and seems to reflect more aggressive histological and clinical behaviors." (PMID 25412182, 2014). "Activation of AKT promotes EMT of colorectal cancer cells, and accumulating evidence also supports a critical role for EGFR, an upstream activator of AKT, in promoting EMT-like phenotypes in mammary epithelial cells, hepatocytes, and lung epithelial cells." (PMID 24945379, 2014). "Afatinib also inhibited growth of nine colorectal cancer cell lines, but its potency varied considerably across lines and was tightly correlated with the expression levels of EGFR, HER2 and ErbB3." (PMID 24643470, 2014). "EGFR protein is overexpressed in 35 to 49% of patients with colorectal cancer with a higher percentage of EGFR overexpression in late stage colorectal tumors." (PMID 25594061, 2014). "These include BRAF V600 mutation for melanoma, EGFR mutation and ALK fusion for lung cancer, HER2 amplification or overexpression for breast cancer, and KRAS mutation for colorectal cancer." (PMID 25593991, 2014). "This mAb is approved for the treatment of advanced colorectal cancer, while the EGFR-TKIs gefitinib and erlotinib have been approved as upfront therapy replacing chemotherapy in late-stage NSCLC patients harboring activating-EGFR mutations." (PMID 25250326, 2014). "Inhibition of EGFR phosphorylation was also shown for the afatinib/nintedanib combination in a colorectal cancer cell line." (PMID 24643470, 2014). "Cetuximab is an IgG1 anti-EGFR antibody targeted against the extracellular domain of EGFR and is approved for use in advanced colorectal cancer and squamous cell carcinoma of the head and neck (SCCHN)." (PMID 25277503, 2014).